FOXO3 (forkhead box O3)
Diseases named in the same sentence as FOXO3 in open-access papers (continued):
Sharing a sentence is not in itself a finding about the gene and the disease.
Infertility (22 papers, 2014 to 2025). "Constitutively active FOXO3 was found to cause infertility, suggesting that nuclear FOXO3 is essential for dormancy regulation but only at a sufficient level." (PMID 36531957, 2022). "In contrast, when the oocyte-specific FOXO3 was overexpressed in mice, the mice showed infertility caused by the retardation of oocyte growth and follicular development, indicating that FOXO3 suppressed the activation of ovarian follicles." (PMID 33102482, 2020). "FOXO3 knock-out mice exhibit global activation of primordial follicles, resulting in premature depletion and infertility." (PMID 40822959, 2025). "On the other hand, FOXO3 knockout mice exhibit global activation of primordial follicles, resulting in premature follicular depletion and subsequent infertility, while overexpression of constitutively active FOXO3 increases ovarian reproductive capacity." (PMID 40822959, 2025). "Consistently, female mice that were generated with disruptions of FOXO3 exhibited age-dependent infertility and had abnormal ovarian follicular growth." (PMID 38700571, 2024). "FoxO3 has been shown to regulate reproduction as FoxO3 null female mice exhibit impaired ovarian follicular development and infertility." (PMID 37941908, 2023). "In mice, Foxo3-null females show abnormal ovarian follicular development leading to degeneration and age-dependent infertility (around 12 weeks)." (PMID 31303978, 2019). "Additionally, FoxO3-KO mice, although viable, demonstrate infertility due to dysfunctional ovarian follicular development during aging along with dysfunctional muscle regeneration." (PMID 34631216, 2021). "Lack of FoxO3 affects lymph proliferation and inflammation in diverse tissues and is also associated with age-associated infertility and decreased number of neural stem cells." (PMID 34631216, 2021). "Of note, selective depletion of FOXO1 and FOXO3 in mouse GC leads to an infertile phenotype characterized by metabolic changes and the production of factors that exerts potent negative feedback to prevent gene expression of pituitary FSH (hub.BN role in the ivF network)." (PMID 34859047, 2021). "FOXO3-specific-depletion in GCs decreases both cell proliferation and apoptosis of GCs and disrupts follicular growth in mice, and a lower mRNA expression of FOXO3 in GCs is involved in infertility in women." (PMID 31671754, 2019). "In addition, FOXO3 depletion in GCs disrupts the normal ovarian follicular growth in mice, and a lower FOXO3 mRNA expression in GCs may lead to infertility in women." (PMID 30759773, 2019). "Based on the described evidence, one of the mechanisms by which FOXO3 affects aging in female individuals may depend on the decreased levels of estrogens in menopause, which would affect ER-mediated FOXO3 expression thereby contributing to premature aging and infertility." (PMID 31303978, 2019). "In contrast, the lack of FOXO3 resulted in uncontrolled follicle activation and early infertility, but did not affect follicular growth after activation." (PMID 36531957, 2022). "Moreover, a mouse model lacking FOXO3 (Foxo3-/-) presents an overall follicular activation, resulting in a premature infertility." (PMID 36430860, 2022).
renal cell carcinoma (22 papers, 2014 to 2025). "In renal cell carcinoma cells, knockdown of IL-13Rα2 or inhibition of IL-13Rα2 with telmisartan increased FOXO3 expression and induced apoptosis of cancer cells." (PMID 39598436, 2024). "IPA confirmed that the target molecules identified in our study (ERK, FOXO1, FOXO3, JNK1, PDCD4, AKT3) form an interactive network with shikonin, which further leads to renal cancer, renal cell carcinoma, and apoptosis." (PMID 41462911, 2025). "In renal cell carcinomas, IL-13Rα2 regulated cancer progression through the regulation of the JAK2/FOXO3 pathway." (PMID 39598436, 2024). "In renal cell carcinoma cells, knock-down of IL4Rα or IL13Rα1 induced cell cycle arrest and apoptosis by suppressing JAK2-mediated phosphorylation of FOXO3." (PMID 33419470, 2021). "The induction of mTOR by FOXO3 stimulates activation of AKT in renal cell carcinoma, while inhibition of FOXO3 activity enhances the sensitivity of renal cell carcinoma cells to PI3K and AKT inhibitors." (PMID 34123834, 2021). "In renal cell carcinoma cells, the silencing of IL4Rα expression reduced interaction between JAK2 and FOXO3 and resulted in stabilizing FOXO3." (PMID 33419470, 2021). "Additionally, adrenomedullin could reduce FDX1 transcription and suppress cuproptosis in renal cell carcinoma (RCC) through promoting p38/MAPK signaling pathway-mediated phosphorylation and nuclear translocation of Forkhead box O3 (FOXO3)." (PMID 38918694, 2024).
Cerebral ischemia (21 papers, 2015 to 2025). Restriction of arterial blood supply to the brain associated with insufficient oxygenation to support the metabolic requirements of the tissue. "Evidence has also shown that activated FOXO3 plays a part in regulating autophagy in the brain, reducing the injury caused by cerebral ischemia-reperfusion, thus providing a new approach for further prevention and treatment of cerebral ischemia." (PMID 35563054, 2022). "Syringin is one naturally occurring compound that exserts neuroprotective effects by phosphorylation/inhibition of FOXO3/NF-κB pathways, thereby reducing neuroinflammation after cerebral ischemia." (PMID 40260403, 2025). "Administration of compounds with antioxidant and anti-inflammatory effects alleviated nerve damage by upregulating Sirt1/FOXO3 and inactivating the NF-κB pathway in mice models of cerebral ischemia." (PMID 40260403, 2025). "Syringin reduces the expression of inflammatory factors(interleukin (IL)‐1β, tumor necrosis factor‐α, and IL‐6), and neutrophil infiltration and increases forkhead box O3A phosphorylation, thereby inhibiting nuclear factor kappa B expression and protecting against cerebral ischemia." (PMID 40566933, 2025). "In a previous study, Fkbp5 was upregulated in cerebral ischemia-reperfusion injury and regulated autophagy via the AKT/FOXO3 signaling pathway." (PMID 40529227, 2025). "To study the functions of miR-19a/b-3p, SPHK1, FoxO3, and SIRT1 in cerebral ischemia, we firstly measured their expression levels during ischemia/ reperfusion (I/R)." (PMID 34051800, 2021).
osteoporosis (21 papers, 2013 to 2026). A condition of reduced bone mass, with decreased cortical thickness and a decrease in the number and size of the trabeculae of cancellous bone (but normal chemical composition), resulting in increased fracture incidence. "miR-29a reversed FoxO3 loss to improve senescence program through targeting Dnmt3b-mediated FoxO3 methylation and increased antioxidant proteins, including Oxr1, to downregulate oxidative stress and DNA methylation, compromising age-induced osteoblast loss and osteoporosis." (PMID 34439496, 2021). "The impaired functionality of FoxOs in bone cells contributes to osteoarthritis, osteoporosis, and other bone diseases, with FoxO1 and FoxO3 being extensively expressed and studied." (PMID 38987770, 2024). "However, FoxO1, FoxO3, and FoxO4 knockout reduced the number of osteoclasts and improved bone remodeling in diabetes-induced osteoporosis." (PMID 38987770, 2024). "In addition, SIRT1 inhibits oxidative stress in BMSCs by deacetylating Forkhead box O3 (FOXO3a), thereby reducing osteoblast senescence and enhancing osteogenic differentiation, leading to the alleviation of osteoporosis." (PMID 37476496, 2023). "In addition, studies have shown that SIRT3 can protect the mitochondria against oxidative damage by regulating FOXO3 deacetylation, and the mitochondrial oxidative stress and mtDNA damage in osteoblasts can be induced by inhibiting the SIRT1-FoxO3a-MnSOD pathway in osteoporosis." (PMID 34847835, 2022).
atherosclerosis (20 papers, 2013 to 2025). A disease characterized by the build-up of fatty material and calcium deposition in the arterial wall resulting in partial or complete occlusion of the arterial lumen. "Secondly, it ameliorates atherosclerosis by regulating endothelial cell proliferation and apoptosis through the modulation of Hippo-forkhead box O3A and phosphoinositide 3-kinase/Akt pathway signaling pathways." (PMID 39047053, 2024). "Regulating apoptosis of vascular smooth muscle cells is another means, whereby FOXO3 protects against atherosclerosis." (PMID 39497655, 2024). "MT acted either through the SIRT3-FOXO3 (forkhead box O3)-PRKN signaling cascade in a murine model of atherosclerosis or through the mitochondrial dynamin-like GTPase (OPA1)/AMPK axis in an ischemia-reperfusion model." (PMID 37107334, 2023). "In contrast, downregulation of FOXO3 reduces NLRP3 inflammasome-mediated endothelial cell pyroptosis in atherosclerosis." (PMID 35085103, 2022). "In the following section, we will discuss the role of FOXO3 in diseases such as atherosclerosis, vascular calcification, hypertension, and vascular aging-related heart diseases, kidney diseases, and cerebrovascular diseases." (PMID 35004893, 2021). "MiR-148a-3p upregulation in atherosclerotic patients suppresses FOXO3 expression and impairs EC proliferation and migration, ultimately aggravating atherosclerosis." (PMID 35004893, 2021). "In addition, FOXO3 integrates the pleiotropic actions of insulin to protect the vascular endothelium from atherosclerosis." (PMID 39497655, 2024). "Although FOXO3 mediates nucleotide-binding oligomerization domain, leucine rich repeat and pyrin domain containing 3 inflammasome activation, which accelerates atherogenesis, the function of FOXO3 in atherosclerosis remains unclear." (PMID 37520709, 2023). "In some cases, FOXO3 promotes ECM degradation which may accelerate the progression of atherosclerosis." (PMID 35004893, 2021). "MiR-30c-5p downregulates FOXO3 expression, inhibiting NLRP3-mediated EC pyroptosis in atherosclerosis." (PMID 35004893, 2021). "Melatonin has been demonstrated to ameliorate atherosclerosis by inhibiting NLRP3 inflammasome, which is regulated by SIRT3/FOXO3/Parkin signaling." (PMID 35004893, 2021). "MiR-148a-3p was selectively upregulated in patients with atherosclerosis and its overexpression promoted proliferation and migration, while inhibiting apoptosis via FOXO4 and FOXO3 modulation, as well as counteracted the release of inflammatory factors in endothelial cells." (PMID 38791128, 2024). "Using this dataset we identified a strong correlation of LMOD1 and FOXO3 transcripts, which suggests that LMOD1 and FOXO3 may be co-regulated during atherosclerosis in vivo." (PMID 30444878, 2018). "Moreover, experiments on low-density lipoprotein (Ldl) receptor knockout mice resulted in the prevention of atherosclerosis when the triple ablation of FOXO1, FOXO3 and FOXO4 was induced in endothelial cells." (PMID 32309538, 2013).
Atrophy (20 papers, 2012 to 2025). Any weakening or degeneration, especially through lack of use. "Phosphorylated Akt, inactivates Foxo3 which in turn inhibits two E3 ubiquitin ligases, Murf1 and Atrogin-1, both of which are implicated in muscle atrophy due to increased protein degradation." (PMID 28951568, 2017). "Collectively, these findings provide direct evidence that stigmasterol confers protection against dexamethasone-induced muscle atrophy by inhibiting the nuclear translocation of FoxO3, thereby restricting its ability to activate the transcription of atrophy-related genes." (PMID 41301469, 2025). "The AKT/P70/ FoxO3 signaling pathway played crucial roles in the myoblast differentiation Importantly, the promoted differentiation and protective effect against atrophy were validated using a rat atrophy model." (PMID 33722298, 2021). "However, MAFbx and Ankrd1 were not significantly upregulated and the fold increase in MuRF1 and Foxo3 was low, indicating that this model is incomplete when compared to atrophy modeling in vivo." (PMID 30906768, 2019). "In models of disuse-induced muscle atrophy, FOXO3 regulated MURF1 expression, promoting the degradation of muscle proteins and exacerbating muscle atrophy." (PMID 41334404, 2025).
Cognitive impairment (20 papers, 2012 to 2025). Abnormal cognition is characterized by deficits in thinking, reasoning, or remembering. "Based on the preliminary clinical study data, FOXO3 is a potential therapeutic target for treating cognitive impairment-related neurodegenerative diseases." (PMID 40260403, 2025). "FOXO3 regulates neuronal dynamics, in this regard, FOXO3 could modulate the onset or amelioration of cognitive impairment in many neurological disorders." (PMID 40260403, 2025). "Mice with UE exhibited cognitive deficits, which were reversed by overexpression of circRNA-PTPN4, whereas silencing FOXO3 exacerbated these deficits." (PMID 38630149, 2024).
diabetic cardiomyopathy (20 papers, 2014 to 2025). Diabetic cardiomyopathy is a disorder of the heart muscle in people with diabetes. "A previous study reported that sustained activation of Foxo1 or Foxo3 leads to diminished insulin responsiveness and impaired glucose metabolism in cardiac myocytes, and Foxo1 activation triggers diabetic cardiomyopathy through downregulation of Irs1 in mice." (PMID 28887535, 2017). "In murine models of diabetic cardiomyopathy, high-intensity treadmill running activates an FGF21/AMPK/SIRT3 cascade that phosphorylates FoxO3, stabilizes mitochondria, and limits oxidative injury." (PMID 40861274, 2025).
Stroke (20 papers, 2013 to 2025). Sudden impairment of blood flow to a part of the brain due to occlusion or rupture of an artery to the brain. "One, a 4‐year prospective cohort study of Dutch men and women aged ≥ 85 years found that a particular FOXO3 haplotype conferred an increased risk for incident stroke and also an increased risk of mortality from CHD, stroke, and all‐cause (total) mortality." (PMID 27071935, 2016). "A cohort study of older American men confirmed the association between FOXO3 variants and cause-specific mortality for major causes of death, including coronary heart disease, cancer, and stroke; specifically, the FOXO3 rs2802292 G-allele was associated with a 10% reduction in all-cause mortality." (PMID 31303978, 2019). "In stroke models, loss of FOXO3 protects neurons and reduces cell death." (PMID 28432353, 2017). "In summary, these results suggested that FOXO3 activation switches on the EXO‐PD‐L1‐HGF‐modulated neuroplasticity in the stroke brain." (PMID 39049677, 2024). "It is known that FOXO3 activation exert numerous beneficial effects in stroke including that FOXO3 signaling pathway activation inhibits oxidative stress-mediated cell death through activation of autophagy." (PMID 39723236, 2024). "Their study supported a critical role for the Akt/FoxO3 signaling pathway in autophagy activation in stroke." (PMID 37323662, 2023). "FoxO3 and eIF5A are just two recent examples of how data obtained from tolerant species can turn about into potential treatments for stroke, at the moment in the experimental setting only." (PMID 34681788, 2021). "FOXO3 viral overexpression induced autophagy in the brain and reduced the infarcted area after stroke in rats." (PMID 34681788, 2021). "Haplotype analyses of FOXO3 revealed that FOXO3 block-A haplotype 2 “GAGC” and haplotype 4 “AAAT” carriers had a higher risk of stroke." (PMID 35004893, 2021). "During experimental stroke, FOXO3 activation is increased in the penumbra area and functions as a protective mechanism against ischemic injury." (PMID 34681788, 2021). "The relation between FOXO3 genotype and cause‐specific mortality was ascertained for major causes of death including coronary heart disease (CHD), cancer, and stroke." (PMID 27071935, 2016). "FOXO3 was shown to exert numerous beneficial effects in stroke." (PMID 39723236, 2024). "For example, Guo and colleagues reported that, during stroke, Hsp70 upregulates FOXO3." (PMID 39723236, 2024). "In addition, FOXO3 overexpression induces autophagy in rat brain cells and reduces infarct size after stroke." (PMID 36399471, 2022). "Among them, Foxo3 and Eif5A were reported to mediate anoxic survival in Drosophila and Caenorhabditis elegans, respectively, and those results were confirmed in experimental models of stroke." (PMID 34681788, 2021). "Physiologically, we now know that the major reason for the increase in lifespan conferred by protective alleles of FOXO3 is protection against death from coronary heart disease (CHD), although in other cohorts such protection may extend to cancer and stroke." (PMID 33260156, 2020). "In neural damage paradigms such as stroke, FOXO3 promotes delayed apoptosis after stress." (PMID 28432353, 2017). "A case:control study of Han Chinese found no relation with CHD, while two other case:control studies found FOXO3 longevity‐allele carriage was associated with lower CHD prevalence (Japanese American males) and with lower CHD and stroke mortality (white males and females)." (PMID 27071935, 2016). "We hypothesized that the longevity‐associated FOXO3 genotype would be associated with a sizable risk reduction for mortality and with one or more major age‐associated clinical causes of death, such as coronary heart disease (CHD), cancer, and stroke." (PMID 27071935, 2016).
myocardial infarction (19 papers, 2017 to 2026). Gross necrosis of the myocardium, as a result of interruption of the blood supply to the area, as in coronary thrombosis. "For instance, FOXO3 activation promotes VSMCs apoptosis, which may result in atherosclerotic plaque instability and rupture, causing myocardial infarction, and cerebral infarction." (PMID 35004893, 2021). "Engineered human mesenchymal progenitor cells (FOXO3-GE-MPCs) can enhance healing after myocardial infarction, with the FOXO3 gene extending their survival." (PMID 39592532, 2024). "Cardiac-specific PRMT1 ablation induces myocardium hypertrophy and heart attack through CaMKII dysregulation, while skeletal muscle–specific Prmt1 KO leads to muscle atrophy via hyperactivated FOXO3 with enhanced energy deprivation." (PMID 35921899, 2022). "For instance, recent studies have shown that FOXO3 genetically engineered human mesenchymal progenitor cells confer better therapeutic efficacy in a mouse model of myocardial infarction." (PMID 35883611, 2022). "For example, AET upregulated IGF-1 levels through activated Akt and ERK1/2 signaling while reducing forkhead box O3 (FoxO3) mRNA levels in the skeletal muscle of myocardial infarction model." (PMID 33066240, 2020). "For example, the white wine component, n-tyrosol pretreatment could confer cardioprotection against an ischemic insult in rat model of myocardial infarction through the activation of AKT/FOXO3/SIRT1 pathway." (PMID 28112228, 2017).
nasopharyngeal carcinoma (19 papers, 2014 to 2025). A carcinoma arising from the nasopharyngeal epithelium. "In another study, Shou and colleagues reported that low expression of FOXO3 was associated with poor clinical stage, increased metastasis, and poor clinical outcomes in nasopharyngeal carcinomas (NPC)." (PMID 37174744, 2023). "In nasopharyngeal carcinoma, SIRT2 mediates the deacetylation of FoxO3, resulting in FoxO3 inactivation." (PMID 39778006, 2025). "For example, it has been shown that in EBV-positive advanced nasopharyngeal carcinoma cells, which exhibit type II latency, EBV LMP1 modulates the PI3K/AKT/FoxO3 pathway, resulting in the accumulation of FoxO3 phosphorylation." (PMID 36016282, 2022). "Similarly, SIRT2-mediated FOXO3 deacetylation has also been implicated in lapatinib response and sensitivity, and that SIRT2 can specifically antagonise the cytotoxicity of lapatinib through mediating FOXO3 deacetylation in both sensitive and resistant nasopharyngeal carcinoma (NPC) cells." (PMID 32372224, 2020).